FGFR2 (fibroblast growth factor receptor 2)
Diseases named in the same sentence as FGFR2 in open-access papers (continued):
Sharing a sentence is not in itself a finding about the gene and the disease.
pancreatic cancer (continued). "Based on data that has attributed cellular functions to fibroblast proliferation in other tissues, we investigated a panel of ten central regulators of cell proliferation (c-Myc, Cyclin D1, Cyclin E1, FGF2, FGFR2, EGFR, EGF, FGF1, FGFR1 and VEGFA) in pancreatic cancer-associated fibroblasts (CAFs)." (PMID 38678032, 2024). "In addition, we also showed that FGFR1 and FGFR2 are key receptors in regulating pancreatic cancer stemness." (PMID 32457900, 2020). "As a result, cancer cells acquire metastatic properties, suggesting that FGF10/FGFR2-IIIb-signalling may promote migration of pancreatic cancer cells through induction of TGF-β1 expression." (PMID 18594526, 2008). "This suggests that FGF10 and FGFR2-IIIb are promising candidates as target molecules for new therapy against pancreatic cancer, and that therapeutic agents directed against these molecules may improve the prognosis of patients with this disease." (PMID 18594526, 2008). "In this study, we show that FGF10/FGFR2-signalling has an important role in pancreatic cancer progression, and we suggest that these results may lead to a new therapy and a better prognosis for patients with pancreatic cancer." (PMID 18594526, 2008). "In the FIGHT-101 clinical trial, one of five patients with pancreatic cancer showed a partial response to anti-FGFR1-3 treatment (pemigatinib); this case was positive for FGFR2::USP33 fusion." (PMID 38542259, 2024). "The most common cancer types where FGFR2 fusion was detected were GC (N = 7, 46.7%), followed by common bile duct (CBD) cancer (N = 5, 33.3%), HCC (N = 1, 6.7%), pancreatic cancer (N = 1, 6.7%), and sarcoma (N = 1, 6.7%)." (PMID 35342406, 2022). "Multiple studies have assessed the ability of certain biomarkers, such as BRCA in pancreatic cancer, IDH1 or FGFR2 in biliary tract cancer and microsatellite instability or NTRK fusions in an agnostic tumour fashion, to predict response to treatment." (PMID 36008616, 2022). "When applied to a large collection of published pancreatic cancer samples (n = 803), Arriba identified a variety of driver fusions, many of which affected druggable proteins, including ALK, BRAF, FGFR2, NRG1, NTRK1, NTRK3, RET, and ROS1." (PMID 33441414, 2021). "Taken together, our results suggest that miR-23a partially promotes pancreatic cancer EMT and metastasis by targeting ESRP1 and regulating CD44 splicing as well as FGFR2 IIIb and FGFR2 IIIc mRNA levels." (PMID 29137308, 2017). "In pancreatic cancer, FGF10 is found in stromal cells, close to the tumor cells, and is thought to interact with FGFR2-IIIb on the tumor cells, thereby inducing cell migration and invasion." (PMID 21767389, 2011). "To examine the expression pattern of FGFR2 and FGF10 in pancreatic cancer tissues, we performed immunohistochemical staining of 76 tissue samples of invasive pancreatic ductal carcinoma and of normal pancreatic tissues." (PMID 18594526, 2008). "The expression pattern of FGF10 and FGFR2 in cancerous tissue and the poor prognosis of patients with high FGFR2 expression in cancer cells indicate that a stromal cell–epithelial cell interaction through FGF10/FGFR2 signalling might induce the malignant properties of pancreatic cancer." (PMID 18594526, 2008). "There are other FGFR2 inhibitors such as pemigatinib and infigratinib which have been tested in cholangiocarcinoma but not in pancreatic cancer." (PMID 38607041, 2024). "We described four FGFR2 fusion-positive PDAC patients who exhibited excellent clinical outcomes with FGFR inhibitors and illustrated the landscape of FGFR fusions and SVs in a large cohort of pancreatic cancers." (PMID 39289482, 2024). "Dovitinib, a potent FGFR multikinase inhibitor, achieved a preclinical anticancer effect in pancreatic cancers with heightened FGFR signaling, suggesting that the efficacy may be most pronounced in cancer cells overexpressing FGFR2." (PMID 37893023, 2023).
pancreatic cancer (continued). "Though studies have already shown that SOX2 induction by FGF and FGFR2 activation inhibits osteoblast differentiation, we propose that FGFR inhibition can also be an effective scheme for indirect inhibition of SOX2 in pancreatic cancer." (PMID 32457900, 2020). "In pancreatic cancer tissues, cancer cells expressed FGFR2 at various levels, but did not express FGF10." (PMID 18594526, 2008). "Notably, among the eight evaluable patients with pancreatic tumors in FIGHT-207, seven patients had FGFR fusions in the context of the KRAS wild-type background, highlighting the importance of testing for FGFR2 fusions in this population with few therapeutic options." (PMID 38710951, 2024). "Though the regulation of FGF2 and FGFR2 on SOX2 has been already reported in the development phase, we were the first to demonstrate that FGFR signaling regulates the protein stability of SOX2 through AKT and promotes its nuclear localization, thus enhancing stemness in pancreatic cancer." (PMID 32457900, 2020). "We reported that expression of FGFR2 IIIb and one of its major ligands, FGF7, correlated with venous invasion, vascular endothelial growth factor A (VEGF-A) expression, and a poor prognosis and may promote venous invasion and tumor angiogenesis in pancreatic cancers." (PMID 22701813, 2012).
melanoma (33 papers, 2009 to 2026). A malignant, usually aggressive tumor composed of atypical, neoplastic melanocytes. "FGFR2 mutations have been described in various melanoma subtypes, including ALM or desmoplastic melanomas." (PMID 37373134, 2023). "Reduced FGFR2 expression has been observed in multiple cancer types, including bladder, prostate, and liver cancer, and deleterious mutations in FGFR2 have been implicated in melanoma." (PMID 35887382, 2022). "A new variant of FGFR2 with a mutation leading to Gly542Glu was reported in BRAFV600E melanoma patient during ongoing treatment with dabrafenib, a BRAFV600E inhibitor, as an example of intratumor clonal evolution resulting in the development of resistance." (PMID 31167513, 2019). "Although loss-of-function mutations are not common in cancer, these type of aberrations (more than 20 different point mutations) have been found in FGFR2 in some melanoma cell lines and uncultured primary and metastatic tumors." (PMID 31167513, 2019). "The loss-of-function (LOF) FGFR2 kinase domain mutations identified in melanoma tumors cell lines include E636K, M640I, I642V, R759Q, E475K, D530N, A648T, and G701S." (PMID 24817905, 2014). "There is as yet too limited data on the correlative responses of melanomas with FGFR2, PTEN/AKT or KIT mutations." (PMID 19949544, 2009). "Notably, 78% of the FGFR2 LoF mutations recurrently found in COSMIC also occurred in malignant melanoma, further pointing toward a subtype-specific relevance of FGFR LoF mutations." (PMID 41361008, 2026). "Interestingly, it was reported that 10% of melanoma tumours and cell lines harbour mutations in the fibroblast growth factor receptor 2 (FGFR2) gene and, what is more, the mutation pattern reflects those induced by UV radiation." (PMID 38473753, 2024). "The loss-of-function mutation A649T in the FGFR2 kinase domain was identified in melanoma." (PMID 30577533, 2018). "A loss of FGFR2 function is also shown to contribute to melanoma." (PMID 28129744, 2017). "However, there is at least one report indicating that some melanoma cell lines demonstrate FGFR2 loss of function." (PMID 26224133, 2015). "In contrast, loss-of-function mutations of FGFR2 have been reported in melanomas." (PMID 22701813, 2012). "In metastatic RPMI7951 melanoma cells, calcitriol treatment led to an upregulation of FGFR2 mRNA levels." (PMID 40791737, 2025). "Very interestingly, we also noticed that our two melanoma cell lines responded differently to the active form of vitamin D, 1,25(OH)2D3 in terms of the change in the mRNA levels of FGFR2 in the experimental conditions used." (PMID 38473753, 2024). "Further, FGFR2 is frequently found up-regulated in melanoma, its expression level increasing with tumor progression, and is suggested to be involved in mediating cell proliferation, survival and migration." (PMID 37047539, 2023). "Subgroup analyses showed that the mutation frequencies of melanoma regarding FGFR1, FGFR2, FGFR3 and FGFR4 ranked 1st, 2nd, 2nd, and 2nd across all cancers, respectively." (PMID 36426352, 2022). "Loss-of-function mutations in FGFR2 and activating mutations in FGFR4 have been connected with melanoma." (PMID 31167513, 2019). "FGFR1 and to some extent FGFR4 are exceptional in contrast to FGFR2-3, and these receptors are expressed in the majority of melanomas." (PMID 31167513, 2019). "Deregulation of FGFR2 gene has been reported in different human pathologies, such as melanoma and thyroid, breast, lung, gastric and ovarian cancers, in which up or downmodulation of KGFR expression has been observed in epithelial cells." (PMID 23613863, 2013). "Most importantly, we noticed an increase in the mRNA level for FGFR2 in RPMI7951 melanoma cells treated with each of our tested FGFR inhibitors and 1,25(OH)2D3 (p < 0.05 for both) or with 1,25(OH)2D3 alone (p < 0.05), but not for monotreatment with CPL304110 nor AZD4547." (PMID 38473753, 2024).
melanoma (continued). "Similarly, melanoma patients harboring FGFR2 Mut had a pronounced survival advantage over those with FGFR2 Wt (mOS: 60.00 months vs. 31.20 months; HR 0.60, 95%CI 0.37-0.88; P = 0.0366)." (PMID 36426352, 2022). "Additionally, FGFR2 promotes melanoma metastasis and recently, the implication of FGFR3 in melanoma growth, metastasis, and EMT behaviors was elucidated, through modulation of phosphorylation levels of ERK, AKT, and EGFR." (PMID 33918490, 2021). "As FGFR2 could induce melanoma growth arrest through interaction with stroma, its inhibition might promote melanoma invasion." (PMID 31167513, 2019). "FGFR2 is also overexpressed by the majority of melanoma cell lines." (PMID 30577533, 2018). "Taking A375 advanced melanoma cells as an example, we detected and validated mutations in BRAF, FGFR2 and mTOR that could reasonably be expected to associate with Vemurafenib (BRAFi (V), hereafter), Vargatef (FGFR2i (Va)) and Everolimus (mTORi (E))." (PMID 26327537, 2015). "FGFR2 is a RTK that may mediate growth arrest in melanoma through interactions with stroma so its inactivation may promote tissue invasion." (PMID 19949544, 2009). "Therefore, it has been suggested that rather than serving as predisposition indicators, genetic aberrations in FGFR2 and FGFR4 might be used as potential biomarkers of melanoma progression." (PMID 31167513, 2019). "Kurniawan and coworkers examined the fibroblast growth factor receptor 2 (FGFR2) as a target for use in the diagnosis and treatment of melanoma." (PMID 35892711, 2022). "Semiquantitative analysis of cDNA from melanoma cells and the fibroblast cell line MainUro revealed that FGFR1 is expressed in all analysed cell lines, while FGFR2-4 are expressed variably." (PMID 30237393, 2018). "We investigate gene dosage effects of Vegfr2, Fgfr1, and Fgfr2 in three independent mouse models of tumorigenesis: two-stage skin chemical carcinogenesis, and sub-cutaneous transplantation of B16F0 melanoma and Lewis Lung Carcinoma (LLC)." (PMID 30283071, 2018). "While other genes (e.g. CDKN2C, CDKN2A, MITF, BAP1, PTEN, ERBB4, and FGFR2, etc.)are mutated with some frequency in melanoma, no common recurring mutations in these genes are observed or the function of observed mutations are unknown; therefore these genes were not included in our screen." (PMID 22536370, 2012). "Interestingly, an increase in the FGFR2 protein level was observed in melanoma cells treated with CPL304110, while an addition of 1,25(OH)2D3 not only reversed this effect, but vastly decreased the protein level of FGFR2 compared to the untreated cells." (PMID 38473753, 2024). "Interestingly, in A375 melanoma cells, CPL304110 treatment increased the FGFR2 protein level and its phosphorylation, while addition of 1,25(OH)2D3 very strongly decreased the level of both, and the effect was time dependent." (PMID 38473753, 2024). "In a large nested case-control study of Caucasian women, however, neither mutations in FGFR2 nor in FGFR4 has been found as contributing to an inherited predisposition to three skin cancer types, including melanoma, SCC, and BCC." (PMID 31167513, 2019). "It has been suggested that the inhibition of FGFR2 activity contributes to melanoma; however, the mechanism(s) is not clear, and reintroduction of FGFR2 failed to suppress melanoma cell proliferation." (PMID 31167513, 2019). "Interestingly, treatment of melanoma cells with CPL304110 or AZD4547 compounds did not affect the mRNA level of FGFR2." (PMID 38473753, 2024). "In this regard, EGFR, PTEN, ESR1, FGFR2 and ERBB2 were more frequently detected in CSF ctDNA than in blood in a cohort of NSCLC and BC as well as in patients with melanoma and negative CSF cytology." (PMID 34207653, 2021).
breast tumors (27 papers, 2010 to 2024). "Another study reported an association between the expression of FGFR2 and the number of breast tumor initiating cells." (PMID 35176995, 2022). "In another study, low expression of FGFR2 was associated with lower numbers of breast tumour-initiating cells." (PMID 27236187, 2016). "Accordingly, increased expression of FGFR2 mRNA was observed in total RNA isolated from breast tumors of patients homozygous for the risk allele as compared to homozygotes for the major allele." (PMID 21767389, 2011). "Moreover, a study by Bane and colleagues reported that BRCA2-associated breast tumors are characterized by an increased expression of fibroblast growth factor 1 and fibroblast growth factor receptor 2 compared to BRCA1-associated breast tumors." (PMID 31244284, 2019). "In conclusion, we further refine the influence of variants in the FGFR2 locus with respect to molecular characteristics of breast tumors, in that they are more strongly associated with estrogen receptor status among cancers without amplification of the HER2 gene." (PMID 27764800, 2016). "Loss of FGFR2 resulted in marked suppression of breast tumor growth." (PMID 23300950, 2013). "Moreover, the increased risk conferred by the minor FGFR2 allele associates most strongly in oestrogen receptor alpha positive (ERα) breast tumours, suggesting a potential interaction between ERα and FGFR signalling." (PMID 24265722, 2013). "We next investigated whether loss of FGFR2 affects the differentiation potential of the breast tumor cells." (PMID 23300950, 2013). "However, in microdissected breast tumours FGFR2 mRNA and protein levels were reduced in tumour cells in comparison with paired normal breast epithelium, suggesting that tumourigenesis is associated with reduced FGFR2 expression." (PMID 27236187, 2016). "This agrees with other published data where the FGFR2 expression was higher in breast tumours that are ER+PR+ and ER+PR− compared to ER−PR− tumours, although FGFR2 has been found to be high in TNBC as well, which can also be seen in our study." (PMID 39596875, 2024). "Second, activated FGFR2 also plays a role in promoting the receptor recycling, which leads to the migration of breast tumors." (PMID 35668376, 2022). "Common oncogenic drivers such as CCND1 and FGFR1 or FGFR2 were amplified in the primary breast tumours and can be considered early events in these patients’ tumours." (PMID 32792481, 2020). "This overexpression is confirmed by the study of Rebbeck that reported FGFR2 over expression occurs in 10-15% of breast tumors, but FGFR2 expression is lower in normal breast tissue in someone who has T allele." (PMID 31759353, 2019). "The SIGNAL/PHARE cohort confirmed the association between FGFR2 locus and ER+ tumors, further restricting this association with HER2-negative breast tumors." (PMID 28830573, 2017). "The aim of our study was to gain new insights into the role of private somatic mutations in FGFR2 and FGF10 in breast tumor development." (PMID 23527311, 2013). "To validate FGFR2 oncogenic function in MMTV-PyMT breast tumors, we transduced primary MMTV-PyMT breast tumor cells with lentiviral short hairpin RNAs (shRNAs) targeting FGFR2 (shFGFR2)." (PMID 23300950, 2013). "The expression and amplification of FGFR2 has long been known to be elevated in 5–10% of breast tumors." (PMID 23527311, 2013). "These two isolated populations (FGFR2+ and FGFR2−) of human breast tumor cells were injected in the mammary fat pad of NOD/SCID mice." (PMID 23300950, 2013). "Restoration of FGFR2 rescued the defects in TIC pool maintenance, bipotency, and breast tumor growth driven by FGFR2 knockdown." (PMID 23300950, 2013). "It has been known for many years that FGF8 and FGF10, both ligands for FGFR2, are overexpressed in human breast tumors, suggesting that antibodies to screen for active FGFR2 would be very useful." (PMID 23343422, 2013).